CADM1 (cell adhesion molecule 1)
Diseases named in the same sentence as CADM1 in open-access papers (continued):
Sharing a sentence is not in itself a finding about the gene and the disease.
small cell lung carcinoma (7 papers, 2017 to 2025). Small cell lung cancer (SCLC) is a highly aggressive malignant neoplasm, accounting for 10-15% of lung cancer cases, characterized byrapid growth, and early metastasis. "At the same time, CADM1 cytoplasmic structural domain mutants are excellent diagnostic markers and therapeutic targets for small cell lung cancer." (PMID 36835189, 2023). "In small-cell lung cancer, researchers have identified a single-chain variable fragment specific to CADM1 in this phenotype and have developed an antibody therapy targeting it." (PMID 38895237, 2024). "Cell Adhesion Molecule 1 (CADM1) has been reported to influence the development of small cell lung cancer through its ability to inhibit the proliferation and metastasis of the disease." (PMID 36835189, 2023). "We found that v8/9 CADM1 is significantly more sensitive to shedding than v8 CADM1 in human small cell lung carcinoma SBC-5 cells and canine epithelial MDCK cells." (PMID 28393893, 2017). "CADM1, also known as TSLC1, IGSF4, SgIGSF, and SynCAM, belongs to the immunoglobulin superfamily and was initially identified as a tumor regulator in small cell lung cancer (SCLC)." (PMID 34395444, 2021).
autism (6 papers, 2015 to 2024). Persistent deficits in social interaction and communication and interaction as well as a markedly restricted repertoire of activity and interest as well as repetitive patterns of behavior. "CADM1 was reported as an autism-associated gene and its knockout would lead to smaller cerebellum and decreased synapse of PKCs63." (PMID 38409116, 2024). "CADM1 is also active in the brain where it is involved in synaptic adhesion and has been linked to autism." (PMID 28482049, 2017). "Our discovery suggested the potential role of CADM1 in the organization of PKCs during the early development and the disturbance of this distribution may also underpin the autism caused by CADM1 mutation." (PMID 38409116, 2024). "In fact, the CADM1-knock out mice exhibit small cerebellums with decreased numbers of synapses with Purkinje neuron cells, which show some similar behaviors associated with autisms." (PMID 25647412, 2015). "Accordingly, CADM1 synaptic receptor complex may be associated with autisms pathogenesis locating on the dendrites of neuron cells." (PMID 25647412, 2015). "The current knowledge regarding the potential link between ASDs and ER stress is minimal and mainly based on autism-associated mutations in CNTNAP2 and the synaptic adhesion protein CADM1." (PMID 26621873, 2016). "Furthermore, the autism-related mutations of CADM1 may bring defective membrane trafficking at the mouse neuronal cell surface, suggesting that a link between impaired synaptogenesis and the molecular pathogenesis of autisms." (PMID 25647412, 2015). "This puts MDGA2 in line with other neuronal cell adhesion molecules of the immunoglobulin family, such as contactins, NRCAM, CADM1 and LRFN5 that are implicated in axon migration and guidance and were associated with autism." (PMID 25572423, 2015).
gastric cancer (6 papers, 2004 to 2022). A primary or metastatic malignant neoplasm involving the stomach. "CADM1 expression in gastric cancer is low, and its overexpression significantly suppresses tumor metastasis." (PMID 34395444, 2021).
glioblastoma (6 papers, 2014 to 2022). The most malignant astrocytic tumor (WHO grade IV). "Exosomal delivery of miR-148a to T98G glioblastoma cells results in cell proliferation and metastasis by downregulation of the cell adhesion molecule 1 (CADM1) and activation of the STAT3 pathway." (PMID 35884411, 2022). "Furthermore, CADM1 expression is associated with poor median survival and cancer progression in GBM patients, which suggests that CADM1 has an essential role in glioblastoma proliferation and metastasis." (PMID 34395444, 2021). "CADM1 expression is lower in glioblastoma in comparison to normal brain tissues." (PMID 34395444, 2021). "In addition, similarly to CADM1, N-cadherin is shed at its ectodomain by ADAM10 in glioblastoma cells, and this process requires PKCα activity." (PMID 24964098, 2014). "However, this study only exhibited the enrichment of miR-148a in the exosomes derived from T98G cells and the negative correlation of CADM1 with exosomal miR-148a in patients with glioblastoma." (PMID 33117083, 2020).
leukemia (6 papers, 2012 to 2023). A malignant (clonal) hematologic disorder, involving hematopoietic stem cells and characterized by the presence of primitive or atypical myeloid or lymphoid cells in the bone marrow and the blood. "Taken together, CADM1, negatively correlated with miR-1246, was deficient in drug-resistant leukemia cells and relapsed leukemia patients." (PMID 37814227, 2023). "Higher expression of miR-1246 and lower expression of CADM1 might be risk factors for leukemia." (PMID 37814227, 2023). "Evidently decreased expression of CADM1 was observed in relapsed primary leukemia patients and chemo-resistant cell lines." (PMID 37814227, 2023). "Further experimental researches still need to be performed to verify the feasibility of miR-1246 and CADM1 in chemo-resistant or relapsed leukemia treatments." (PMID 37814227, 2023). "Our results from Western blot displayed that the relative expression of CADM1 in relapsed patients was clearly lower than that in the first diagnosed leukemia patients." (PMID 37814227, 2023). "Consistent with which, CADM1 was also downregulated in chemo-resistant leukemia cells than in their parental cells." (PMID 37814227, 2023). "Our results exhibited that the expression level of CADM1 was lower in blood of patients with relapsed leukemia than in their first diagnosed blood samples." (PMID 37814227, 2023). "Our study discovered that CADM1 was involved in the cell cycle regulation and impaired the effect of miR-1246 on promoting cell cycle progression in chemo-resistant leukemia cells." (PMID 37814227, 2023). "Above all, our results demonstrated that CADM1 attenuated the role of miR-1246 in promoting cell cycle progression and cell survival, thus influencing multidrug resistance within chemo-resistant leukemia cells via CDKs/Cyclins." (PMID 37814227, 2023). "Compared with donors, the mRNA expression level of CADM1 in first diagnosed leukemia patients was decreased." (PMID 37814227, 2023). "Because we found specific expression of CADM1 in ATLL cells, we initially determined the expression of CADM1 in leukemia samples from patients with various types of ATLL and in ATLL-related cell lines by quantitative PCR." (PMID 30837480, 2019). "However, few studies reported CADM1 in leukemia for its complexity, and TCGA database only showed that its expression in acute myeloid leukemia (LAML) was notably lower than that in other tumors." (PMID 37814227, 2023). "Even lower levels of CADM1 expression could be found in the blood of patients with partial or complete relapsed leukemia than that of patients with first diagnosed leukemia." (PMID 37814227, 2023). "Interference with CADM1 could significantly attenuate the cell cycle arrest effect of miR-1246 suppression on chemo-resistant leukemia cells via influencing CDKs/Cyclins axis." (PMID 37814227, 2023). "Thus, CADM1 played an indispensable mediating role in the biological function of miR-1246 on leukemia." (PMID 37814227, 2023). "Therefore, higher expression of miR-1246 combined with lower expression of CADM1 might serve as a potential therapeutic target for patients with clinically chemo-resistant and relapsed leukemia." (PMID 37814227, 2023). "Rescue experiments revealed that interference with CADM1 could markedly heighten the cell viability, drug resistant ability to ADM and alleviate the decrease of cell activity caused by miR-1246 inhibition in chemo-resistant leukemia cells." (PMID 37814227, 2023). "Some rescue experiments were conducted by transfecting in-NC + si-NC, in-miR-1246 + si-NC, or in-miR-1246 + si-CADM1 into chemo-resistant leukemia cells to illuminate whether CADM1 participated in the process of miR-1246 playing its biological function in chemotherapy-resistant leukemia cells." (PMID 37814227, 2023).
leukemia (continued). "Interference with CADM1 could reduce the increased drug sensitivity induced by miR-1246 inhibition, and notably restore drug resistance by promoting cell cycle progression and cell survival via regulating CDKs/Cyclins complexes in chemo-resistant leukemia cells." (PMID 37814227, 2023). "The mRNA and protein level of CADM1 downregulated in chemo-resistant K562/ADM and HL-60/RS cells than in their parental sensitive leukemia cells." (PMID 37814227, 2023). "In order to clarify the relationship among CADM1, chemotherapy resistance and leukemia, RT-qPCR and Western blot were used to determine CADM1 expression in leukemia patients and cells with or without chemo-resistance." (PMID 37814227, 2023).
pancreatic cancer (6 papers, 2014 to 2022). "Many studies reported CADM1 as a tumor suppressor in several cancer types, including ovarian, breast, and pancreatic cancers, and the loss of CADM1 expression is closely associated with cancer progression and metastasis." (PMID 35805896, 2022). "High expression of CADM1 promotes the apoptosis of pancreatic cancer cells, while miR-196b inhibits apoptosis and promotes the proliferation of pancreatic cancer by targeting the 3′-UTR region of CADM1." (PMID 34395444, 2021). "Overexpression of miR-196b in PC tissues can increase the late apoptosis of pancreatic cancer cells by targeting CADM1." (PMID 28904340, 2017). "Indeed, downregulation or loss of CADM1 expression is frequently observed in various cancers, such as NSCLC, HCC, cervix, prostate and pancreas cancer, especially in those with LNM and DM." (PMID 29262659, 2017).
bladder cancer (5 papers, 2021 to 2024). "In a study considering bladder cancer and normal tissues, CADM1 expression was suppressed by methylation, and its expression was significantly lower in cancer tissues." (PMID 34395444, 2021). "Similarly, in bladder cancer, upregulated CADM1 promotes cancer cell apoptosis by promoting caspase-3 and Bax protein expression, thereby inhibiting tumor growth." (PMID 34395444, 2021). "For example, the cell adhesion molecule 1 (CADM1), which acts as a tumor suppressor, appeared to be under‐expressed within bladder carcinoma tissues." (PMID 34105305, 2021).
colorectal cancer (5 papers, 2014 to 2021). A primary or metastatic malignant neoplasm that affects the colon or rectum. "In terms of clinicopathology, CADM1 methylation is highly correlated with T stage and Dukes’ stage of colorectal cancer." (PMID 34395444, 2021).
esophageal cancer (5 papers, 2015 to 2022). A primary or metastatic malignant neoplasm involving the esophagus. "Liang and colleagues found that CADM1/TSLC1 gene could inhibit the proliferation of esophageal cancer cell line Eca109 and block the transition from G1 phase to S phase in cell cycle, thus inducing apoptosis." (PMID 26880895, 2016). "In esophageal carcinoma, however, ODZ4 rearranges with Exostosin Glycosyltransferase 2 (EXT2), while ODZ4 rearranges with Cell Adhesion Molecule 1 (CADM1) and Gram Domain containing 1b (GRAMD1B) in chronic lymphocytic leukemia." (PMID 35011736, 2022). "The drawback of the study is that the expression of CADM1/TSLC1 in recurrence tissues was not provided, primarily due to low biopsy rate in patients with recurrent esophageal carcinoma." (PMID 26880895, 2016).
laryngeal squamous cell carcinoma (5 papers, 2016 to 2022). A squamous cell carcinoma that arises from the larynx. "Considering clinical prognosis, lower CADM1 expression is associated with severe laryngeal squamous cell carcinoma." (PMID 34395444, 2021). "In addition, CADM1 mRNA and protein expression is associated with laryngeal squamous cell carcinoma cases." (PMID 34395444, 2021). "In humans, hsa-miR-424-5p was reported to be upregulated in laryngeal squamous cell carcinoma and promoted proliferation, migration, and invasion by targeting the tumor suppressor, CADM1." (PMID 36142686, 2022).
endometrial cancer (4 papers, 2021 to 2025). Primary or metastatic malignant neoplasm involving the endometrium (mucous membrane that lines the endometrial cavity). "Furthermore, the expression of CADM1 has a role in extracellular matrix adhesion and has been shown to promote endometrial cancer progression." (PMID 36434155, 2023).
fibrosis (4 papers, 2017 to 2023). the formation of excess fibrous connective tissue in an organ or tissue in a reparative or reactive process. "It has been previously shown that miR-21 is negatively associated with SPRY1 in the pro-fibrotic pathway and enhanced cardiac fibrosis via CADM1/STAT3 pathway in a model of rat cardiac fibroblasts." (PMID 33804922, 2021). "Our studies further support miR-21 acts as important regulators in participate in cardiac fibrosis pathological, enhances cardiac fibrotic remodeling and fibroblast proliferation via CADM1/STAT3 pathway." (PMID 28335740, 2017). "CADM1 expression is decreased in cardiac fibrosis tissue and fibroblast and may regulate STAT3 controlling cellular proliferation and, therefore, cardiac fibrosis development." (PMID 37894937, 2023). "More importantly, miR-21 inhibitor repressed cardiac fibrosis progression, miR-21 may be a better alternative to directly inhibit CADM1 expression in cardiac fibrosis." (PMID 28335740, 2017). "Other findings showed that miR-21 promoted cardiac fibrosis via the TGF-β/Smad7 signaling pathway after myocardial infarction and via the CADM1/STAT3 pathway in patients with atrial fibrillation." (PMID 35118144, 2021).
nasopharyngeal carcinoma (4 papers, 2012 to 2021). A carcinoma arising from the nasopharyngeal epithelium. "CADM1 plays an important role in nasopharyngeal carcinoma, and its expression is downregulated in nasopharyngeal carcinoma tissues." (PMID 34395444, 2021).
squamous cell carcinoma (4 papers, 2007 to 2022). A carcinoma arising from squamous epithelial cells. "Regarding tumor histology, 86.4% of the 19 squamous cell carcinomas were positive for CADM1 and /or MAL." (PMID 36010947, 2022). "In squamous cell carcinoma, CADM1 is a direct target of miR-424-5p, and the overexpression of miR-424-5p promoted tumor development." (PMID 33419290, 2020). "Squamous cell carcinoma is a keratinocytes origin malignancy, and the reduction in CADM1 might impair the adhesion ability of lymphocytes, due to the loss of the scaffolding molecule for immune cells to promote inflammation in the epidermis." (PMID 33419290, 2020). "The actual role of CADM1 in squamous cell carcinoma is largely unknown, however, the degree of CADM1 expression in squamous cell carcinoma might also affect the infiltration of inflammatory cell migration into the tumor." (PMID 33419290, 2020). "Therefore, miR-424-5p-targeted indirect suppressive reactions to CADM1 in squamous cell carcinoma might also become a therapeutic tool for the suppression of CADM1 in squamous cell carcinoma." (PMID 33419290, 2020). "In squamous cell carcinoma, HPV16/18-positive patients with cervical squamous cell carcinoma showed significant differences in the hypermethylation of CADM1." (PMID 33419290, 2020). "Squamous cell carcinomas revealed frequent promoter methylation, that is in >40% of cases, of CDH13 (nine out of 16: 56.3%), DAPK1 (nine out of 16: 56.3%), MGMT (15 out of 16: 93.8%) and CADM1 (nine out of 16: 56.3%)." (PMID 17971771, 2007).
T-cell leukemia (4 papers, 2018 to 2023). A malignant disease of the T-lymphocytes in the bone marrow, thymus, and/or blood. "CADM1 is an adhesion molecule which is implicated in tumor invasion of adult T-cell leukemia cells and acute myelocytic leukemia cells." (PMID 34257559, 2021). "SPRi analysis identified a new interaction between CADM1 and CADM4, where this heterophilic interaction was shown to be involved in morphological spreading of adult T-cell leukemia (ATL) cells expressing CADM1 when incubated on CADM4-coated glass." (PMID 30131958, 2018).
acute myeloid leukemia (3 papers, 2009 to 2023). Acute myeloid leukemia (AML) is a group of neoplasms arising from precursor cells committed to the myeloid cell-line differentiation. "In contrast, CADM1 is upregulated in adult T cell leukemia and acute myelocytic leukemia, contributing to the enhancement of cell-cell adhesion to the vascular endothelium, tumor growth and tissue infiltration." (PMID 34257559, 2021).
adenoma (3 papers, 2014 to 2023). A neoplasm arising from the epithelium. "Recurrent somatic mutations altering residues in the transmembrane domain of CADM1 are identified in aldosterone-producing adenomas." (PMID 37291193, 2023).
Anxiety (3 papers, 2015 to 2022). Intense feelings of nervousness, tension, or panic often arise in response to interpersonal stresses. "Cadm1 knockout mice show anxiety-like behaviour in the open-field and light-dark transition tests, as well as motor coordination and gait impairments in rotarod and footprint tests." (PMID 35456420, 2022). "Cadm1 is highly expressed in the dendritic arbor of Purkinje neurons and Cadm1 knockout mice demonstrate reductions in cerebellar size and abnormal social behaviors, abnormal vocalizations, increased anxiety, and abnormal motor coordination." (PMID 26388713, 2015).
atopic dermatitis (3 papers, 2015 to 2019). "Mast cells and nerves often jointly regulate tissue inflammation and pathology; mast cells can secrete NGF and CADM1 is an important component of mast cell-nerve synapses that regulate the pathophysiology of atopic dermatitis lesions." (PMID 31052404, 2019). "The cell adhesion molecule 1 (CADM1) regulates mast cell-neuron synapses in atopic dermatitis." (PMID 28158195, 2017). "We have also demonstrated pathological roles of CADM1 in atopic dermatitis." (PMID 26636084, 2015). "Taken together, these data suggest that neuron-mast cell adhesion (so called “neuro-immune interaction”) might be strengthened in atopic dermatitis through an increased expression of CADM1 in mast cells." (PMID 26636084, 2015). "Furthermore, an increased expression of CADM1 is involved in the development of atopic dermatitis by promoting the neuro-immune interaction." (PMID 26636084, 2015).
cervical intraepithelial neoplasia (3 papers, 2022 to 2024). "CADM1 methylation was detected in 38 (73.1%) and MAL methylation in 25 (48.1%) across all cervical dysplasia patients." (PMID 36010947, 2022). "The methylation of CpG sites for both CADM1 and MAL have previously been indicated as potential biomarkers in HPV-related cervical intraepithelial neoplasia (CIN) with reports of 78% specificity and 70% sensitivity in women with HRHPV infections for histological CIN3+30." (PMID 35241698, 2022).
COVID-19 (3 papers, 2021 to 2026). A disease caused by infection with severe acute respiratory syndrome coronavirus 2. "On the other side, CD99 signaling in the NK cells and CADM1 signaling in the CD8+ TCM were observed in the COVID-19 patients but not in healthy or recovered individuals." (PMID 36532041, 2022).
cutaneous squamous cell carcinoma (3 papers, 2020 to 2022). "Decreased CADM1 expression in cutaneous squamous cell carcinoma demonstrates poor survival rates." (PMID 33419290, 2020). "However, the correlation between CADM1 expression and prognosis in cutaneous squamous cell carcinoma (cSCC) patients remains unclear." (PMID 34064472, 2021).
esophageal squamous cell carcinoma (3 papers, 2005 to 2021). Esophageal squamous cell carcinoma (ESCC) is a type of esophageal carcinoma (EC) that can affect any part of the esophagus, but is usually located in the upper or middle third. "In esophageal squamous cell carcinoma, the OS (overall survival) and PFS (progression-free survival) of the CADM1 positive group was higher than those of the negative group, and CADM1 could have a potential role in prognosis." (PMID 34395444, 2021).